BTG2 (BTG anti-proliferation factor 2)
Diseases named in the same sentence as BTG2 in open-access papers (continued):
Sharing a sentence is not in itself a finding about the gene and the disease.
tumor (continued). "In this work, we validated that BTG2 expression level was reduced in BC tissues, which is in line with its tumor-suppressive function reported in previous reports." (PMID 34082648, 2021). "Another tumor suppressor, BTG2, is known to suppress proliferation, and is typically inhibited in cancers." (PMID 33768972, 2021). "BTG2 has been identified as an anti-proliferative gene since 1991, and it is recognized as a tumor suppresser in diverse malignancies." (PMID 34699325, 2021). "Tumor-derived exosomal miRNA-27a was found to promote angiogenesis in PaCa via B-cell translocation gene 2 (BTG2)." (PMID 34243775, 2021). "Of these, ADM, DCBLD2, EREG, ITGA5, MIF, MMP14, and TREM1 were associated with poor prognosis and significantly increased in tumor, while BTG2 was related to favorable prognosis and decreased in tumor." (PMID 35002712, 2021). "For instance, it is plausible that the downregulation of 3 upstream regulators of SOD2 (IGFBP7, KL, BTG2), which are potential tumor suppressors, leads to an increase in SOD2 when the malignancy of IPMN worsens." (PMID 32842508, 2020). "Numerous studies show that miR-21-5p promotes carcinogenesis and tumor progression by targeting genes encoding PDCD4, PTEN, BTG2, FasL, IGFBP3, TGF-β1, FBXO11, and TIMP3." (PMID 33396321, 2020). "At the same time, the average tumor volume and weight were significantly increased by silencing BTG2, which was abrogated by overexpressing circRNA_000864." (PMID 33425718, 2020). "In support of this possibility, BTG2 protein was expressed at lower level in tumor tissues compared with normal tissues." (PMID 31959200, 2020). "For example, Btg2 a tumor suppressor, which arrests cells at the G1/S and the G2/M transition, increases apoptosis." (PMID 32271843, 2020). "Xenotransplantation of nude mice was conducted to detect the effects of circRNA_000864, miR-361-3p, and BTG2 on tumor growth." (PMID 33425718, 2020). "The results showed that the proliferation and metastasis of tumor cells were significantly increased, indicating that BTG2 is a mediator in which miR-6875-3p functions." (PMID 30621734, 2019). "Previous studies have reported that BTG2 can inhibit the proliferation, invasion and metastasis of tumor cells." (PMID 30621734, 2019). "In this study, we showed that BTG2 is a tumor suppressor that is downregulated in EC, expanding our understanding of BTG2." (PMID 31885582, 2019). "TSPX overexpression in LNCaP cells and TSPX-high clinical prostate specimens are associated with elevated expression levels of two tumor suppressors SEMA3B and BTG2." (PMID 30863497, 2019). "In this study, miR-6875-3p was found to be abnormally highly expressed in HCC tissues and cell lines, and negatively correlated with BTG2 expression while positively correlated with tumor staging, size, degree of differentiation, and vascular invasion of HCC." (PMID 30621734, 2019). "We found that miR-6875-3p were elevated expressed in HCC tissues and cell lines, and negatively correlated with BTG2 expression, while positively correlated with tumor staging, size, degree of differentiation, and vascular invasion of HCC." (PMID 30621734, 2019). "This activity causes the depression of the tumor-suppressor genes BTG2/Tis21/PC3 and LATS1/2, promoting tumor growth in vitro and in vivo." (PMID 30923703, 2019). "Low level of BTG2 in breast tumor thus correlates with increased tumor grade, disease progression and decreased overall survival." (PMID 30350856, 2019). "There is evidence that BTG2, as a tumor suppressor gene, plays an vital role in regulating the differentiation, proliferation, apoptosis and migration of tumor cells." (PMID 30621734, 2019). "The up-regulated genes were associated with apoptosis induction (BTG2, TP73 and PIDD1) and cell cycle arrest (RPRM and CDNK1A), consistent with the tumor suppressive function of PKNOX2." (PMID 30745575, 2019). "Studies have shown that BTG2 plays a crucial role in tumor occurrence and development as a tumor suppressor gene." (PMID 30621734, 2019).
tumor (continued). "Using a paired Student's t‐test, BTG2 was significantly downregulated in tumour tissues (fold change = 0.55, P = 7.79 × 10−16)." (PMID 29656435, 2018). "As a tumor suppressor in many types of malignancies, BTG2 is involved in proliferation, cell cycle progression, apoptosis, and DNA damage repair." (PMID 29310680, 2018). "Both PDCD4 and BTG2 are described to play a tumor suppressor role in several cancers and are downregulated in PDAC." (PMID 29464088, 2018). "BTG2 has been identified as a tumor suppressor of the BTG/TOB gene family, which inhibits cell proliferation, invasion and promotes apoptosis in several tumors, including TNBC." (PMID 29310680, 2018). "Tumor-associated genes, MTSS1, NKX6-2, and BTG2 had CpGs that were highly significant in heavy smokers but showed little or no significance in light smokers." (PMID 27935972, 2016). "In fact, treatment of mice with 177Lu-HuIgG resulted in a higher tumor expression of BTG2 than did the 177Lu-trastuzumab." (PMID 27196891, 2016). "BTG2 enhances MnSOD expression in HeLa cells after treatment with doxorubicin and MnSOD has been suggested as a new type of tumor suppressor." (PMID 24047462, 2013). "Learning how BTG2 up-regulates MnSOD is important for understanding the antioxidant and the tumor suppressive roles of B Cell Translocation Gene 2 in normal and cancer cells." (PMID 24047462, 2013). "Further studies in independent tumour sets are needed to validate and establish BTG2 protein expression as a prognostic marker." (PMID 20553615, 2010). "The proportion of BTG2 protein expression was higher in tumours from 5-year overall survivors than among the tumours from deceased patients." (PMID 20553615, 2010). "Nevertheless, BTG2 was significantly down-regulated in tumours from dead patients compared to tumours from alive patients, both in overall expression and cell membrane specific expression." (PMID 20553615, 2010). "Protein expression of BTG2 was found to be significantly more prevalent in tumours from alive patients compared to tumours from dead patients." (PMID 20553615, 2010). "These include critical cell cycle regulating tumor suppressors such as cyclin dependent kinase inhibitors CDKN1C (p57) and the cell cycle and differentiation associated BTG2." (PMID 20927380, 2010). "The BTG anti-proliferation factor 2 gene plays a key role in cell proliferation, apoptosis, and cell growth and may also function as a tumor suppressor." (PMID 40650017, 2025). "However, the expression level of BTG2 was significantly correlated with the degree of tumor differentiation (P = 0.013), suggesting that patients with low BTG2 expression were more likely to exhibit poorly differentiated tumors." (PMID 41441930, 2025). "Notably, BTG2, a radiation-responsive gene, has been reported to undergo dose-dependent upregulation in tumor cells following radiotherapy." (PMID 40313959, 2025). "This has led to the hypothesis that BTG2 might exert a similar effect in cells, which are involved in enrichment in tumor tissue and draining lymph nodes." (PMID 40313959, 2025). "In addition, as previously found in tumor cells, BTG2 can maintain more Src in a reduced state by reducing the level of ROS in mitochondria, thereby reducing the phosphorylation of FAK molecules." (PMID 40313959, 2025). "There may be potential utility of serum tryptase levels as a non-invasive biomarker for BTG2-low mast cell and tumor prognosis, further validation in a larger cohort is needed." (PMID 40313959, 2025). "Whether targeting NOX2 and BTG2 can simultaneously influence both cell-autonomous tumor behaviors and broader stromal interactions represents a highly compelling research topic." (PMID 41441930, 2025). "In addition, miR-21 was reported to the regulate tumor suppressor and regulator of B-cell differentiation BTG2 and E3 ubiquitin ligase PELI1 which are known to regulate c-REL levels." (PMID 38539461, 2024).
tumor (continued). "Additionally, patients with LUAD who have lower expression of the BTG2 gene in their tumor tissue tend to have a poorer prognosis." (PMID 39148731, 2024). "Meanwhile, the immune cells which were positively related to the expression of BTG2 may play an anti-tumor role." (PMID 37006240, 2023). "We observed significant differences in APRO family genes among different immune subtypes, with P values less than 0.001, suggesting that the APRO family was related to tumor immunity, and the expression level of the BTG2 ranks first in the overall immune subtypes of C1–C6." (PMID 38062199, 2023). "Several findings have shown that BTG2 has a tumor-inhibiting impact." (PMID 37415745, 2023). "This suggests that abnormal expression of BTG2 is closely related to tumor formation, suggesting that tumor formation may be related to BTG2 expression." (PMID 36591524, 2022). "BTG2 is a tumour suppressor that is downregulated in some cancer cell types." (PMID 35522946, 2022). "The findings of this study indicated that BTG2 suppresses RCC tumor growth." (PMID 36591524, 2022). "BTG2 inhibited NC tumor growth compared to that of the shBTG2 group." (PMID 34485119, 2021). "Furthermore, in line with previous studies that reported BTG2 as a tumor suppressor involved in multiple biological processes of cancer, our study identified BTG2 as a prognostic protection gene in PDAC." (PMID 35002712, 2021). "A series of studies demonstrated that BTG2 mainly acted as a tumor suppressor in cancer." (PMID 34861847, 2021). "BTG2 is a tumor suppressor in B-ALL and a known target of p5352." (PMID 34764253, 2021). "Accordingly, the downregulation of BTG2 could induce the proliferation and invasion of LSCC cells, suggesting that BTG2 has a tumour-suppressive effect in LSCC." (PMID 34187411, 2021). "The function of BTG2 in tumor growth is well explored in several reports." (PMID 33598424, 2020). "We also corroborated that EMT is involved in BTG2‐regulated tumour metastasis." (PMID 32746503, 2020). "Moreover, several tumor suppressors, including BTG2, TUSC1, BAK1, LATS2, FZD6 and PPP2R1B, were regarded as common targets of TET3." (PMID 32209730, 2020). "Furthermore, downregulation of Btg2 in microglia led to increased cell proliferation, which suggests that tumor cells deliver specific cargo to regulate their TME to create a more favorable microenvironment for glioma tumor progression." (PMID 32038644, 2019). "The role of BTG2 during tumor progression seems to be more unambigious." (PMID 30350856, 2019). "Moreover, a role for BTG1 and BTG2 as tumor suppressors in both lymphoid malignancies and solid tumors is emerging." (PMID 30350856, 2019). "BTG2 functions as a tumor suppressor or promoter in various human malignancies." (PMID 31223310, 2019). "Altogether, these findings establish BTG2 as a tumor suppressor and show that its downregulation, as it is frequently observed in solid tumors, may synergize with oncogenic signals, such as Ras, to induce malignant transformation." (PMID 30350856, 2019). "NKX6-2 and BTG2 (B-Cell Translocation Gene 2) are candidate tumor suppressor genes." (PMID 27935972, 2016). "Furthermore, we identified tumour suppressors, including BTG2, TUSC1, BAK1, LATS2, FZD6 and PPP2R1B, as common targets of TLX and TET3." (PMID 26838672, 2016). "In that sense, it is worth to note that BTG2-induced MnSOD expression might be one of the early events of tumor suppression by maintaining the integrity of mitochondria." (PMID 24047462, 2013).
tumor (continued). "Inhibition of miR-21 could upregulate the expression of a miRNA-target tumor suppressor gene such as protein tyrosine phosphatase (PTEN) and B cell translocation gene 2 (BTG2), and thereby decreases tumor progression." (PMID 24326156, 2013). "Additionally, mast cells with low BTG2 expression could induce an increased proportion of αSMA-positive myofibroblasts, which enhance tumor invasiveness and metastatic potential by altering the glycosylation patterns of tumor cells." (PMID 40313959, 2025). "In addition, BTG2 modulates transcription factors involved in tumor proliferation, suggesting that its high expression in MCs may represent an OSCC-driven mechanism to evade immune responses." (PMID 40061903, 2025). "Additionally, BTG2 may play a role in the polarization of M2-type macrophages and the tumor microenvironment." (PMID 40496561, 2025). "For patients with negative axillary lymph node ultrasound findings, the number of mast cells and BTG2 expression levels in tumor tissue can be assessed to determine whether additional radiotherapy is needed to improve the immune suppression in micrometastatic lymph nodes." (PMID 40313959, 2025). "In our research, we demonstrated that low BTG2 expression in mast cells within lymph nodes indicates an immunosuppressive microenvironment, which may correlate with an increased likelihood of distant tumor recurrence." (PMID 40313959, 2025). "It has been reported that BTG2 could play an anti-tumor role in a variety of ways." (PMID 37006240, 2023). "Therefore, the NF-κB signaling pathway may be involved in rescuing from apoptosis in BTG2 overexpression A549 cells and helping tumor cells survive." (PMID 36157236, 2022). "While tumor suppressors are commonly inactivated by genetic mutations, deleterious mutations in BTG2 have not to date been identified, suggesting its downregulation may be a result of epigenetic reprogramming." (PMID 33768972, 2021). "Finally, we examined the potential role of BTG2 as a tumor suppressor in NSCLC." (PMID 31959200, 2020). "A recent study revealed that BTG2 inhibited the activation of FAK pathway by down-regulating reactive oxygen species (ROS) in tumor cell mitochondria, but the specific mechanism of miR-6875-3p-BTG2 axis regulating FAK/Akt pathway in HCC cells remains unclear and needs to be further explored." (PMID 30621734, 2019). "Despite its tumour-suppressor effects, mutations in BTG2 have not been detected, suggesting that epigenetic mechanisms could be involved in modulating BTG2 expression in cells." (PMID 26394836, 2015). "Tumor tissues from 66 ESCC patients were analyzed for NOX2 and BTG2 expression using immunohistochemistry to determine their clinical significance." (PMID 41441930, 2025). "Mast cells with low BTG2 expression have enhanced migratory capacity and are preferentially recruited to lymph nodes by cytokines such as CCL5, secreted by tumor cells during metastasis." (PMID 40313959, 2025). "A similar mechanism was observed in CC, where VIRMA negatively regulated the mRNA stability of BTG2 via an m6A-YTHDF2-dependent pathway, thereby facilitating malignant tumor progression." (PMID 40723784, 2025). "In contrast, BTG2, MT1E, and PHYHD1 were identified as protective factors in our model, potentially functioning as suppressors of tumor progression." (PMID 40496864, 2025). "PC cell-derived exosomal miR-27a, along with regulated B‐cell translocation gene 2 (BTG2), enhanced tumour angiogenesis." (PMID 38341827, 2024). "We found that CX3CR1+ macrophages enhanced the expression of the corresponding target tumor inhibitory genes, such as BTG2, EGR2, ERG3, NR0B1, and SDC4, on NR5A1+ tumor cells." (PMID 38658971, 2024). "The protein levels of DDIT4, TUBA4A, and PTTG1 were markedly elevated in tumor tissues, whereas SLA and BTG2 were notably diminished compared to normal tissues." (PMID 38200058, 2024).
tumor (continued). "Collectively, various genes involved in cancer progression were regulated by the combination treatment of Vactosertib and T1-44, and in particular, BTG2 is a key regulator of EMT-induced inhibition of cell migration and increased tumor cell death." (PMID 36765032, 2023). "StromalScore and ImmunoScore were used to analyze the correlation between APRO (TOB1, TOB2, BTG1, BTG2, BTG3 and BTG4) expression and tumor purity and tumor microenvironment characteristics." (PMID 38062199, 2023). "The results of our study showed that when BTG2 was low expression and SerpinB5 was high expression in LUAD, the macrophage M0 in the tumor microenvironment increases during tumorigenesis." (PMID 37006240, 2023). "The upstream regulator analysis of cisplatin revealed an increase in FAS, BTG2, SESN1, and CDKN1A, and the involvement of the tumor microenvironment pathway." (PMID 38003016, 2023). "BTG2, a member of the antiproliferative BTG/Tob family, is known as a tumor suppressor in various cancer types." (PMID 36765032, 2023). "BTG2 is a member of the BTG/Tob protein family, which acts as a tumour suppressor by controlling mRNA stability." (PMID 35522946, 2022). "BTG2 (BTG anti-proliferation factor 2) is the first gene found in the BTG/TOB gene family and exerts a tumor suppressor effect in various cancers." (PMID 35870960, 2022). "In contrast, increased BTG2 and LAMP3 expression are accompanied by increased sensitivity of tumor cells to chemotherapeutic agents, such as axitinib, oxaliplatin, and fluorouracil." (PMID 35372503, 2022). "The expression of CCL20, CD70, PCDH7, DCBLD2, and MMP14 genes were remarkably more elevated within LUAD samples than adjacent non-tumorous tissues, where PIK3R5, RNF144B, BTG2, CD69, and MEP1A genes were the opposite." (PMID 36497225, 2022). "Labelled by benign signatures, subclusters 1 and 2 similarly overexpressed metabolism‐related genes and tumour suppressors (KLF6, EGR1, GC, FAM46A, ZFP36, BTG2, etc.)." (PMID 35075805, 2022). "Exosomal miR-365 from M2 macrophages not only regulates chemoresistance but it also promotes PDAC development through suppressing B-cell translocation gene 2 (BTG2) expression and activating FAK/AKT pathway in tumour cells." (PMID 34671031, 2021). "The tumor suppresser, 12-O-Tetradecanoyl phorbol-13-acetate (TPA)-inducible sequences 21 (TIS21), an ortholog of B-cell translocation gene 2 (BTG2), inhibited TNBC cell growth and invasion via activation of Akt1 and not Akt2." (PMID 34298660, 2021). "BTG2, a member of the BTG/TOB family, was the first gene to be identified as a recognized tumor suppressor gene with anti-proliferation properties." (PMID 34217312, 2021). "This is in agreement with previous studies showing that miR-21 and miR-27a acted as cooperative repressors of a network of tumor suppressor genes that included PDCD4, BTG2, and NEDD4L." (PMID 34208765, 2021). "SRXN1‐regulated ROS modulated p65, which inhibited BTG2 expression and ultimately led to migration and invasion by HCC cells, as well as tumour metastasis in vivo." (PMID 32746503, 2020). "Among the several tumor suppressors, BTG2/TIS21 gene was primarily focused due to its targeting activity on actin nucleator, Dia19." (PMID 31138781, 2019). "In contrast, the upregulated DEGs included both caner-drivers/oncogenes, e.g. FGFR1 and MAP3K8, and tumor suppressors, e.g. SEMA3B and BTG2." (PMID 30863497, 2019).